CD5L (CD5 molecule like)
Description:
Secreted protein that acts as a key regulator of lipid synthesis: mainly expressed by macrophages in lymphoid and inflamed tissues and regulates mechanisms in inflammatory responses, such as infection or atherosclerosis. Able to inhibit lipid droplet size in adipocytes. Following incorporation into mature adipocytes via CD36-mediated endocytosis, associates with cytosolic FASN, inhibiting fatty acid synthase activity and leading to lipolysis, the degradation of triacylglycerols into glycerol and free fatty acids (FFA). CD5L-induced lipolysis occurs with progression of obesity: participates in obesity-associated inflammation following recruitment of inflammatory macrophages into adipose tissues, a cause of insulin resistance and obesity-related metabolic disease. Regulation of intracellular lipids mediated by CD5L has a direct effect on transcription regulation mediated by nuclear receptors ROR-gamma (RORC). Acts as a key regulator of metabolic switch in T-helper Th17 cells. Regulates the expression of pro-inflammatory genes in Th17 cells by altering the lipid content and limiting synthesis of cholesterol ligand of RORC, the master transcription factor of Th17-cell differentiation. CD5L is mainly present in non-pathogenic Th17 cells, where it decreases the content of polyunsaturated fatty acyls (PUFA), affecting two metabolic proteins MSMO1 and CYP51A1, which synthesize ligands of RORC, limiting RORC activity and expression of pro-inflammatory genes. Participates in obesity-associated autoimmunity via its association with IgM, interfering with the binding of IgM to Fcalpha/mu receptor and enhancing the development of long-lived plasma cells that produce high-affinity IgG autoantibodies (By similarity). Also acts as an inhibitor of apoptosis in macrophages: promotes macrophage survival from the apoptotic effects of oxidized lipids in case of atherosclerosis. Involved in early response to microbial infection against various pathogens by acting as a pattern recognition receptor and by promoting autophagy. Promotes recovery from acute kidney injury (AKI) by accumulating on necrotic cell debris within the kidney proximal tubules following AKI and interacting with HAVCR1 expressed on the surface of injured kidney tubular epithelial cells. This enhances HAVCR1-mediated phagocytosis of intraluminal necrotic debris and contributes to kidney tissue repair. Also enhances necrotic debris uptake by kidney macrophages in a HAVCR1-independent manner (By similarity).
Synonyms: hAIM; API6; Spalpha; AIM; CT-2; PRO229; SP-ALPHA
Tractability: Antibody: UniProt places it where antibodies can reach, with high confidence; UniProt predicts a signal peptide or a membrane-spanning region; its Gene Ontology location is reachable by antibodies, with medium confidence.
Gene: Protein-coding gene on chromosome 1 (157,830,911 to 157,898,256, reverse strand). Ensembl gene ENSG00000073754.
Subcellular location: Secreted; Cytoplasm
Pathways (Reactome):
Vesicle-mediated transport: Scavenging by Class B Receptors
Gene Ontology:
Molecular function: protein binding
Biological process: cellular defense response; regulation of complement activation
Cellular component: blood microparticle; cell surface; extracellular region; cytoplasm; plasma membrane; membrane
Genetic constraint (gnomAD): Loss-of-function variants: 39 observed, 44.38 expected, observed/expected ratio (o/e) 0.88, 90% interval 0.68 to 1.15. The upper end of that interval is the gene's LOEUF score, 1.15, which puts it in group 5 of 6, group 1 being the genes least tolerant of losing a copy. Missense variants: 431 observed, 456.12 expected, observed/expected ratio (o/e) 0.94, 90% interval 0.87 to 1.02. Synonymous variants: 192 observed, 179.63 expected, observed/expected ratio (o/e) 1.07, 90% interval 0.95 to 1.21.
Homologues: Orthologues: chimpanzee CD5L (99% identical), macaque CD5L (90% identical), mouse Cd5l (69% identical), rat Cd5l (68% identical), dog CD5L (66% identical), guinea pig CD5L (63% identical), zebrafish si:dkey-14d8.20 (39% identical), zebrafish si:ch211-51a6.2 (34% identical), zebrafish si:ch73-127m5.1 (34% identical), Drosophila melanogaster Loxl2 (8% identical). Paralogues in human: SSC5D (47% identical), DMBT1 (44% identical), CD163 (42% identical), SCART1 (41% identical), CD163L1 (40% identical), SSC4D (40% identical), PRSS12 (33% identical), CD6 (30% identical), LOXL3 (25% identical), LOXL2 (24% identical), LOXL4 (24% identical), LGALS3BP (19% identical), and 3 more.
Diseases named in the same sentence as CD5L in open-access papers:
CD5L is named in the same sentence as 104 diseases in open-access papers, as found by Europe PMC text mining. Sharing a sentence is not in itself a finding about the gene and the disease. The quoted sentences say what the papers report.
atherosclerosis (16 papers, 2013 to 2026). A disease characterized by the build-up of fatty material and calcium deposition in the arterial wall resulting in partial or complete occlusion of the arterial lumen. "CD5L has been implicated in the pathogenesis of several infections, atherosclerosis, and is linked to insulin resistance in obesity." (PMID 33028031, 2020). "CD5L encodes a secreted protein that is mainly expressed by macrophages in lymphoid and inflamed tissues and regulates the mechanisms underlying inflammatory responses, such as those involved with infection or atherosclerosis." (PMID 34001107, 2021). "Interestingly, of the top ten most upregulated genes in aortas of PCSK9DY+WD mice, six are associated with atherosclerosis in experimental and clinical studies: Cd5L, which is expressed mostly by macrophages in inflamed tissues, is upregulated in stable plaques." (PMID 38469142, 2024). "Thus, CD5L acts as a key factor in the initiation of obesity-associated chronic inflammation leading to insulin resistance, which results in the progression of atherosclerosis and contributes to future CV events." (PMID 34629330, 2021). "We found that in undifferentiated, unstimulated monocytes deleted for CD5L, several dysregulated transcripts code for genes involved in cell-to-cell interactions and in the progression of atherosclerosis." (PMID 41660620, 2026). "Intriguingly, among these secreted proteins, PLTP, CD5L, and LPL have been reported to exacerbate or be associated with advanced atherosclerosis, whereas IL18BP is anti‐atherogenic." (PMID 33231376, 2021). "CD5L is involved in lipid homeostasis (especially with respect to obesity and inflammatory responses), atherosclerosis, insulin resistance, and metabolic syndrome." (PMID 32756554, 2020). "It is worth noting that CD5L may exert dual or even opposing effects in diseases such as atherosclerosis, and the potential side effects of long‐term intervention—particularly on lipid metabolism—were not assessed." (PMID 41040887, 2025). "Moreover, prior studies have revealed that CD5L is regulated by cholesterol metabolism and promotes atherosclerosis." (PMID 37223476, 2023). "CD5L is involved in macrophage biology and regulation of T cells, specifically T helper 17 (Th17) cells, innate and adaptive immune cells known to be involved in infection, atherosclerosis and cancer." (PMID 36083988, 2022). "Our findings are in line with studies showing that CD5L might be detrimental in metabolic disorders and atherosclerosis, including diabetes and CV events." (PMID 34629330, 2021). "During the last decade, CD5L has gained increasing importance as a critical player in pattern-recognition of microbial components, as well as in controlling key mechanisms in inflammatory responses related to infection, atherosclerosis and cancer." (PMID 34754007, 2021). "CD5L (CD [cluster of differentiation] 5 molecule like) is an important soluble protein proposed to interconnect inflammation with obesity, lipid metabolism and lipidome, insulin resistance, and atherosclerosis." (PMID 32756554, 2020). "Both scavenger receptors, CD5L and CD36, are essential molecules related to inflammatory responses and atherosclerosis mediated by macrophages; while CD36 oxLDL endocytosis prompts foam cell formation, CD5L facilitates CD36-mediated oxLDL uptake." (PMID 34629330, 2021). "CD5L (CD5 molecule-like) is a secreted glycoprotein that controls key mechanisms in inflammatory responses, with involvement in processes such as infection, atherosclerosis, and cancer." (PMID 29593730, 2018).
hepatocellular carcinoma (15 papers, 2017 to 2025). A malignant tumor that arises from hepatocytes. "Surprisingly, CD5L is found to be associated with various diseases such as lipid metabolic disease, hepatocellular carcinoma, fungus induced peritonitis, acute kidney injury and myocardial infarction in later studies." (PMID 34750342, 2021). "The activation of memory CD4 T-cell-associated genes CST7, CD5L, hsa-miR-23b-3p, and hsa-miR-23a-3p may correlate with the prognosis of hepatocellular carcinoma." (PMID 37139238, 2023). "Furthermore, the report revealed literature and database associations among the regulatory role of CD5L and cirrhosis, hepatocellular carcinoma and other liver diseases." (PMID 35102292, 2022). "In addition, CD5L is associated with the hepatic fibrosis and hepatocellular carcinoma." (PMID 34750342, 2021). "In patients with hepatocellular carcinoma, CD5L concentrations correlate to relapse‐free and overall survival." (PMID 39345206, 2025). "Proteomic analyses have identified altered CD5L levels from inflammation to cancer, including hepatocellular carcinoma and lung adenocarcinoma." (PMID 40565234, 2025). "Its anti-HCC activity in mice was also shown through its prevention of hepatocellular carcinoma with administration of CD5L." (PMID 36494696, 2022). "Although the role of CD5L in the oncogenesis of BC is not fully understood, a recent work found that CD5L is upregulated in hepatocellular carcinoma and promotes liver cancer cell proliferation and antiapoptotic responses." (PMID 33182810, 2020). "In the recent reports, apoptosis inhibitor of macrophage (AIM, also called CD5L) prevents obesity, hepatocellular carcinoma and acute kidney injury." (PMID 28743989, 2017). "Notably, elevated CD5L has been observed in the serum of humans with cirrhotic NAFLD or hepatocellular carcinoma." (PMID 35141703, 2021). "The dysregulation of CD5L has been reported in hepatocellular carcinoma (HCC)." (PMID 36494696, 2022). "In addition, CD5L protein directly activates the JNK signaling pathway in hepatocytes but not in macrophages, which may play important role in promoting hepatocyte damage, exactly as abnormal CD5L accumulation can also lead to kidney and hepatocellular carcinoma cells injury." (PMID 34750342, 2021).
Obesity (15 papers, 2014 to 2026). Accumulation of substantial excess body fat. "Based on these results, the authors proposed the regulation of CD5L levels as a potential therapeutic strategy to treat inflammatory diseases associated with obesity, such as metabolic syndrome." (PMID 33920819, 2021). "Supporting these observations, obese CD5L-deficient mice had lower infiltration of inflammatory macrophages in adipose tissue, which prevented the progression of obesity-associated inflammation both locally and systemically." (PMID 33920819, 2021). "In addition, regulators of immune response were higher expressed, whereas proteins promoting macrophage-infiltration during the progression of obesity-associated inflammation, such as CD5L, were reduced." (PMID 33572949, 2021). "Even obesity, which is associated with a high macrophage infiltration in adipose tissue, might be a risk factor with an important contribution of CD5L levels on epicardial fat." (PMID 32695009, 2020). "CD5L has been shown to have a role in several pathologies, mostly inflammatory diseases, ranging from infections to obesity or cancer." (PMID 36982564, 2023). "Correlations between CRP and BMI in all groups suggest that overweight and obesity increase the intensity of inflammation and potentiate CD5L expression." (PMID 36556186, 2022). "In studies analyzing its possible role in inflammation and obesity, CD5L internalized into adipocytes through CD36, and once in the cytosol, induced lipolysis." (PMID 33920819, 2021). "In this review, we discuss the pathogenesis of obesity-associated inflammatory diseases from the immunological perspective by focusing on the apoptosis inhibitor of macrophage (AIM, also known as Spα and CD5L)." (PMID 24281248, 2014). "CD5L is also known as apoptosis inhibitor 6 (API6) and has been reported to inhibit the activity of fatty acid synthase, in addition to inducing lipolysis during the progression of obesity." (PMID 33808296, 2021).
lung carcinoma (10 papers, 2021 to 2025). "Among these proteins, CD5L was identified as a promising biomarker with high accuracy for diagnosing lung cancer and was also found to be associated with various lung cancer histologies." (PMID 37641132, 2023). "Choi and colleagues observed high levels of CD5L in extracellular vesicles of lung cancer that correlated with those in cancer tissues, suggesting a potential role in the non-invasive diagnosis of lung cancer." (PMID 40565234, 2025). "In lung cancer patients, CD5L is detected in extracellular vesicles of liquid biopsies and positively correlated to tissue concentrations and disease severity." (PMID 39345206, 2025). "Further analysis revealed that only CD5L was significantly upregulated in cancer tissues, suggesting its potential as a biomarker for lung cancer diagnosis." (PMID 40575159, 2025). "Among these, the expression of CD5L only, also known as apoptosis inhibitor 6, is related to that in cancer tissue suggesting its potential application as a lung cancer biomarker." (PMID 36829523, 2023). "Further results showed that only CD5L is significantly upregulated in cancer tissues, which suggested that CD5L can be an effective biomarker for lung cancer diagnosis." (PMID 35158999, 2022). "In Network 2, CD5L was found to be a regulatory molecule and a potential EV biomarker for liquid biopsy due to its synchronized expression in cancer tissues and EVs of lung cancer samples." (PMID 33808296, 2021). "We, therefore, proposed that CD5L represents the key EV molecule among the biomarker candidates, the expression of which corresponds with lung cancer and may represent an effective biomarker in liquid biopsies." (PMID 33808296, 2021). "Cumulatively, the results suggest that CD5L can be used as a lung cancer-specific EV biomarker for liquid biopsy because its expression is linked to cancer origin, and it represents a core regulatory molecule with respect to functions associated with lung cancer." (PMID 33808296, 2021). "The CD5L levels in patient serum-derived EVs may be related to its expression in lung cancer tissues." (PMID 33808296, 2021). "Cumulatively, these results show that EV-derived CD5L may represent a potential biomarker—detected via a liquid biopsy—for the noninvasive diagnosis of lung cancer." (PMID 33808296, 2021). "Moreover, the isolation of EVs from human serum and EV protein profiling could facilitate the use of liquid biopsy for predicting lung cancer progression by measuring CD5L expression in circulating EVs." (PMID 33808296, 2021). "The expression levels of seven proteins (CD5L, CLEC3B, SERFINF1, ITIH4, SAA4, SERFINC1, and C20ORF3 (APMAP)) were found to be significantly increased in serum-derived EVs of lung cancer patients, including AC, SCC, and small cell lung cancer (SCLC)." (PMID 35158999, 2022). "Based on these results, seven proteins, CD5L, CLEC3B, SERFINF1, ITIH4, SAA4, SERFINC1, and C20ORF3 (AMAP) were confirmed as being upregulated in EVs and were therefore considered as potential lung cancer biomarkers." (PMID 33808296, 2021). "However, the fact that CD5L is also expressed in macrophages, which induce local and systemic inflammation, could provide diverse perspectives regarding the origin and regulatory mechanism of EV CD5L in lung cancer." (PMID 33808296, 2021). "Although the abundance ratio of CD5L was not significantly different in both groups, it was previously found to be increased in patients with lung cancer, with its expression correlated to cancer tissues, and CD5L was suggested as a non-invasive biomarker for this type of cancer." (PMID 36982564, 2023).
Cirrhosis (6 papers, 2009 to 2025). A chronic disorder of the liver in which liver tissue becomes scarred and is partially replaced by regenerative nodules and fibrotic tissue resulting in loss of liver function. "The recent identification of CD5L by microarray as one of 30 mRNA transcripts expressed in patients with cirrhosis with a 'high risk' of HCC development was one reason for our focus on this serum protein." (PMID 19656391, 2009). "Certainly some of our HCC patients had markedly high CD5L levels, while those with cirrhosis who had particularly high levels may be at high risk and may yet develop HCC." (PMID 19656391, 2009). "Our results support this notion since we show that circulating CD5L and EV content of lipid mediators are not only altered in cirrhosis vs. healthy subjects but also differ between disease stages, namely compensated vs. decompensated with or without ACLF." (PMID 35330909, 2022). "Of note, lower plasma levels of CD5L were present in patients with cirrhosis of alcohol etiology in comparison to those of hepatitis C virus origin, without reaching statistical significance." (PMID 35330909, 2022). "At a level > 200 ng/ml, CD5L had a specificity for cirrhosis of 96% and a specificity for cancer of 60%." (PMID 19656391, 2009). "In contrast, we found that CD5L was positively associated with IgG but not with IgM or IgA in AD cirrhosis and ACLF." (PMID 35330909, 2022). "As a cirrhosis biomarker, the ROC analysis for CD5L indicates an accuracy of 72%." (PMID 19656391, 2009). "CD5L, a macrophage-derived glycoprotein, increased significantly in chronic hepatitis (CHB and CHC) and cirrhosis (ALC and NALC), modulating inflammation and lipid metabolism." (PMID 40647574, 2025). "Although CD5L was reported to be increased in HCV-related fibrosis and HCV-induced cirrhosis, the few samples (four patients each group) reduced the reliability of the results." (PMID 30755830, 2019). "Our ELISA assay indicated a poor performance for CD5L as a surveillance tool for HCC, but again suggested value for cirrhosis detection." (PMID 19656391, 2009). "A comparison of female versus male cirrhosis patients was conducted, yielding no indication for a sex‐specific difference in CD5L in this disease." (PMID 39345206, 2025). "Our results indicate that circulating EVs were significantly suppressed in cirrhosis, regardless of severity, and showed considerable alterations in CD5L and lipid mediator content as the disease progressed." (PMID 35330909, 2022). "However, serum CD5L was dramatically increased, independently of age, sex, and the presence of necroinflammation, in the serum of individuals with NAFLD cirrhosis relative to those with pre-cirrhotic disease." (PMID 19656391, 2009). "Serum CD5L was assessed in the serum of 45 individuals with steatohepatitis-related HCC and compared to levels in 49 individuals with biopsy proven steatohepatitis-related cirrhosis." (PMID 19656391, 2009). "As CD5L does not increase incrementally with the level or stage of fibrosis, we propose that its dramatic increase in the serum of individuals with a background cirrhosis reflects hepatocyte regeneration, rather than the advanced fibrosis per se." (PMID 19656391, 2009).